CCND1 (cyclin D1)
Diseases named in the same sentence as CCND1 in open-access papers (continued):
Sharing a sentence is not in itself a finding about the gene and the disease.
mantle cell lymphoma (continued). "mTOR directly mediates Cyclin D1 downregulation through glycogen synthase kinase (GSK)-3b in mantle cell lymphoma (MCL)." (PMID 33489922, 2020). "Mantle cell lymphoma (MCL) is a mature B-cell lymphoma, which originates from the inner mantle zone and is characterised by elevated expression of cyclin D1 as a result of the 11q13 translocation." (PMID 31492883, 2019). "Although the process of cyclin D1 nuclear import is insufficiently characterized in mantle cell lymphoma (MCL), the export of cyclin D1 complexes from the nucleus into the cytoplasm is established to be XPO1-dependent." (PMID 28196522, 2017). "Bcl-2 and cyclin D1 translocations found respectively in follicular lymphomas (FL) and mantle cell lymphomas (MCL), occur during V(D)J recombination." (PMID 27729620, 2017). "The overexpression of CCND1 has been indicated in various human B-cell lymphoma subtypes, including mantle cell lymphoma (MCL), DLBCL, and plasma cell myeloma." (PMID 28069005, 2017). "Mantle cell lymphoma (MCL) is a distinct type of non-Hodgkin lymphoma genetically characterized by balanced t(11:14) translocation and cyclin D1 overexpression." (PMID 27626308, 2016). "In mantle cell lymphoma (MCL), the CCND1 gene located on chromosome 11 is usually rearranged to a strong enhancer in the immunoglobulin heavy-chain (IGH) locus on chromosome 14, leading to increased CCND1 transcription and CCND1 protein levels." (PMID 27713153, 2016). "Mantle cell lymphoma (MCL) is a rare but aggressive form of B-cell non-Hodgkin lymphoma characterized by excessive expression of cyclin D1." (PMID 26377148, 2016). "mTOR has indeed been proven an important element in tumorigenesis in mantle cell lymphoma (MCL): its role was confirmed in MCL cell proliferation, mainly by influencing cyclin D1 expression." (PMID 23693095, 2013). "In addition to these notifications, cyclin D1 was also identified as a potentially important antigen for immunotherapy of mantle cell lymphoma as it was proved to be recognized by potent cytotoxic T cells when it was naturally presented by lymphoma cells in the context of HLA - A * 0201 molecules." (PMID 21176227, 2010). "Mantle cell lymphoma (MCL) and multiple myeloma (MM) are two hematological malignancies for which cyclin D1 expression has been recognized as an oncogenic event." (PMID 20459741, 2010). "In addition to examples of tumors in which two different INK4 genes are inactivated, it recently was reported that mantle cell lymphoma, most of which have an IgH translocation that dysregulates CYCLIN D1, become more proliferative when the INK4a/ARF locus is deleted." (PMID 17049078, 2006). "Disruption of these degradation pathways through mutations at either the phosphorylation or sumoylation sites leads to persistent cyclin D1 stabilization, promoting B lymphocyte transformation and a lymphoma-like phenotype reminiscent of mantle cell lymphoma (MCL)." (PMID 41368202, 2026). "In mantle cell lymphoma, ML364 facilitates the degradation of CCND1 and β−catenin, arresting the cell cycle and impeding tumor growth." (PMID 40370434, 2025). "Examples include TRA::MTCP1 for T-PLL, TYK2 rearrangement for T-cell lymphomas; CCND1 and CCND2 rearrangement with IGK and IGL in mantle cell lymphoma; MYC rearrangements and hyperdiploidy in multiple myeloma." (PMID 40361363, 2025). "Given the patient’s prior histopathological diagnosis, additional immunohistochemical tests were performed to confirm mantle cell lymphoma, including CD20, CD3, Ki67, Bcl-2, Bcl-6, MUM1, Cyclin D1, CD23, CD5, and CD10." (PMID 40843808, 2025).
mantle cell lymphoma (continued). "Mantle cell lymphoma expresses B cell markers (CD20 and CD79a), T cell markers (CD5), and cyclin D1." (PMID 38698463, 2024). "The detection of the IGH::CCND1 translocation in the 2023 bone marrow specimen raises questions about whether the patient developed a second lymphoma—mantle cell lymphoma (MCL) or this rearrangement is a manifestation of clonal evolution within CLL." (PMID 39691246, 2024). "More than 40 oncogenes are fused to IGH, including MYC, BCL2 and BCL6, CCND1/2, FGFR3, seen in Burkitt lymphoma, follicular lymphoma and DLBCL, mantle cell lymphoma, and multiple myeloma, respectively." (PMID 37206267, 2023). "Chromosomal translocation in the mantle cell lymphoma (MCL) places the CCND1 under the control of the immunoglobulin heavy chain enhancer, resulting in the abnormal accumulation of cyclin D1 in tumor cells." (PMID 37427143, 2023). "Mantle cell lymphoma (MCL), accounting for 3–10% of non-Hodgkin lymphoma, is a mature B cell lymphoma characterized by cyclin D1 rearrangement." (PMID 38104096, 2023). "Mantle cell lymphoma is a B cell non-Hodgkin lymphoma (NHL), representing 2–6% of all NHLs and characterized by overexpression of cyclin D1." (PMID 37626420, 2023). "Mantle cell lymphoma (MCL) is characterized by monomorphic small to medium-sized lymphoid cells with irregular nuclei and the CCND1 translocation, originating from peripheral B lymphocytes of the inner mantle zone, CD5+, and SOX11+ in the classical form." (PMID 36358737, 2022). "Previously, iron depletion was reported to induce cell cycle arrest by reducing cyclin D1 levels in mantle cell lymphoma cells and by reducing PCNA and cyclin D1 levels in a dose-dependent manner in immortalized Kaposi’s sarcoma cells." (PMID 35631174, 2022). "Consistent with the observations in previous reports, we detected significant upregulation of CCND1 and SOX11 mRNAs in mantle cell lymphoma cases." (PMID 36359790, 2022). "A distinction from follicular lymphoma (positive for CD10 and BCL6), mantle cell lymphoma (CD5, cyclin D1, and SOX11), and chronic lymphocytic leukemia (CD5, CD23, and LEF1) is needed." (PMID 35053607, 2022). "Research into the PF-00477736 CHK1 inhibitor resistant mantle cell lymphoma cell line JEKO-1, showed that resistant cells had a shorter S phase and a reduced expression of cell cycle checkpoint proteins, including cyclin D1." (PMID 36240066, 2022). "Mantle cell lymphoma (MCL) is an incurable and heterogeneous disease characterized by chromosomal t(11:14)(q13;32) translocation and cyclin D1 overexpression." (PMID 35059312, 2021). "This inhibitor suppressed the expression of WNT target genes (CCND1, LEF1 and TCF7) in mantle cell lymphoma (MCL) and strongly impaired cell proliferation and induced apoptosis in vitro in MCL and in acute myeloid leukemia (AML) cell lines." (PMID 34771683, 2021). "The specimens revealed mantle cell lymphoma, with immunohistochemistry stains positive for CD20, Bcl-2, cyclin D1, SRY-box transcription factor-11 (SOX-11), immunoglobulin D (IgD) and immunoglobulin M (IgM) but negative for CD3, CD5, CD10 and CD23." (PMID 34442137, 2021). "CCND1 is commonly translocated to IGH in mantle cell lymphoma (MCL)." (PMID 34210001, 2021). "Mantle cell lymphoma (MCL) is an uncommon lymphoproliferative disorder accounting for 6–7% of non-Hodgkin lymphomas and is characterized by the translocation of the Cyclin D1 gene." (PMID 33466784, 2021). "Biomarkers, including CD5, cyclin D1 and SOX-11, are useful for the differential diagnosis of mantle cell lymphoma from other B-cell NHLs." (PMID 34442137, 2021). "Mantle cell lymphoma (MCL) is an aggressive B-cell lymphoma, molecularly defined by the translocation of CCND1." (PMID 29695239, 2018).
mantle cell lymphoma (continued). "Mantle cell lymphoma is a mature B cell lymphoma with characteristic IGH/CCND1 translocation and/or overexpression of cyclin D1." (PMID 28375188, 2017). "Mantle cell lymphoma expresses B-lymphocyte markers (CD20 and CD79a), T-lymphocyte markers (CD5), and cyclin D1." (PMID 28705174, 2017). "A mantle cell lymphoma with a MYC and CCND1 translocation should still be diagnosed as a mantle cell lymphoma even if the MYC rearrangement has additional clinicopathologic implications." (PMID 26517511, 2015). "Translocations between immunoglobulin genes and BCL2, MYC, and BCL1/CYCLIN D1 are found in the majority of follicular Lymphoma (FL), Burkitt`s Lymphoma (BL), and Mantle Cell Lymphoma, respectively." (PMID 24260260, 2013). "Mantle cell lymphoma (MCL) is a mature, aggressive B-cell lymphoma with a CCND1 translocation, usually presenting at an advanced clinical stage, and commonly involving the lymph nodes, spleen, bone marrow, and extranodal sites (includes the gastrointestinal tract and Waldeyer ring)." (PMID 22953080, 2012). "Immuno histochemistry and immunophenotypic analyses were positive for Cyclin D1, CD20, CD5 and CD 79a, but negative for BCL6, CD23 and CD10, thus confirming the diagnosis of mantle cell lymphoma." (PMID 19646237, 2009). "The presence of cyclin D1b mRNA and protein has been studied in two hemopathies in which cyclin D1 could be present: multiple myeloma (MM) and mantle cell lymphoma (MCL)." (PMID 17022831, 2006). "Mantle cell lymphoma (MCL) is a rare non-Hodgkin’s lymphoma (NHL) subtype characterized by rapid growth of abnormal B-cells in the mantle zone of the lymph node (LN), mainly driven by cyclin D1 overexpression upon the IGH::CCND1 translocation." (PMID 41184633, 2026). "It is known that there are cyclin D1 negative mantle cell lymphomas characterized by an aggressive clinical evolution." (PMID 40506992, 2025). "This highlighted the need for a reliable biomarker to identify cyclin D1-negative mantle cell lymphomas, which tend to exhibit more aggressive clinical behavior." (PMID 40506992, 2025). "Based on the results obtained, the differential diagnosis for this case included CD5-positive MALT lymphoma, cyclin D1-negative mantle cell lymphoma (MCL), or chronic lymphocytic leukemia (CLL)." (PMID 41262807, 2025). "CCND2 and CCND3 rearrangements detected in most cyclin D1-negative mantle cell lymphoma represent a recurrent disease mechanism." (PMID 41374977, 2025). "This is especially the case for chromosome aberrations involving the IG heavy chain (IGH) locus and one of the many partner genes, such as the genes BCL1 (cyclin D1), BCL2, and MYC, which are defining for mantle cell lymphoma, follicular lymphoma, and Burkitt lymphoma, respectively." (PMID 39403025, 2025). "Immuno-phenotypic and Immuno-histochemistry analyses were positive for Cyclin D1, CD5, CD20 and BCL2, but negative for CD10, CD23 and BCL6, which confirms which confirmed the diagnosis of stage IV mantle cell lymphoma with intact bowel resection margins." (PMID 38954973, 2024). "CD5 expression is possible but mantle cell lymphoma (including CCND1-negative MCL) should be excluded." (PMID 37530792, 2024). "For example, CD5 (−) can rule out small lymphocytic lymphoma, Cyclin D1 (−) can rule out mantle cell lymphoma." (PMID 38640287, 2024). "The absence of expression of cyclin D1 distinguishes them from mantle cell lymphomas, and the absence of CD10 expression achieves differential diagnosis from most follicular lymphomas." (PMID 34814897, 2021). "In the case of a cyclin D1+ large B cell lymphoma, immunohistochemistry for CD5, SOX11, and FISH analysis with a CCND1 break-apart probe must be performed in order to rule out a pleomorphic/blastoid mantle cell lymphoma." (PMID 31388760, 2019).
mantle cell lymphoma (continued). "Although the expanded mantle zone was atypical, the B cells in the mantle zone were negative for CD5, CD43, and cyclin D1, hence not supportive of mantle cell lymphoma." (PMID 29387055, 2017). "It appears therefore that SOX11 expression is a highly specific biomarker for cyclin D1- negative mantle cell lymphoma." (PMID 26949534, 2016). "Recently, a rare type of cyclin D1-negative mantle cell lymphoma, which overexpresses cyclins D2 or D3, was identified." (PMID 23675804, 2013). "There are rare forms of mantle cell lymphoma that are negative for cyclin D1 that have indistinguishable features from conventional MCL." (PMID 23691402, 2013). "Immunohistochemically, the low and intermediate grade B-cell lymphomas show the following immunophenotypes: follicular lymphoma, CD5-, CD10 +, CD23 -, CD43 -, cyclin D1 -; MALT lymphoma, CD5-, CD10-, CD23-, CD43+/-, cyclin D1 -; mantle cell lymphoma, CD5+, CD10-, CD23-, CD43 +/-, cyclin D1 +." (PMID 22333190, 2012). "The present tumor is not mantle cell lymphoma, because of negative cyclin D1 which is almost always positive in mantle cell lymphoma." (PMID 22333190, 2012). "The differential diagnosis of CD5-positive MALT lymphoma and cyclin D1-negative mantle cell lymphoma is very difficult." (PMID 22333190, 2012). "The histo morphology and the immunophenotypic analysis were consistent with a mantle cell lymphoma – positive for Cyclin D1, CD20, CD79a and CD5; negative for BCL16, CD23 and CD10." (PMID 19646237, 2009). "Mantle cell lymphoma is an aggressive B cell neoplasm characterized primarily by a monotonous proliferation of small-to-medium-sized lymphocytes coexpressing CD5, CD20, and cyclin D1 epitopes and frequently presents chromosomal translocations, t(11 14) (q13; q32)." (PMID 38698463, 2024). "Mantle cell lymphoma (MCL) is a subtype of Non-Hodgkin lymphoma (NHL) of mature B-cells characterized by translocation, which is typically due to excess expression of Cyclin D1." (PMID 37004047, 2023). "Fluorescent in situ hybridization revealed a CCND1/IGH rearrangement, consistent with a diagnosis of advanced stage mantle cell lymphoma (MCL)." (PMID 36051018, 2022). "IGH-CCND1 is a common translocation observed in mantle cell lymphoma (MCL) and multiple myeloma (MM); when translocated together, the IGH super-enhancers drive CCND1 overexpression." (PMID 35863900, 2022). "Mantle cell lymphoma (MCL) is an uncommon and invasive subtype of non-Hodgkin’s lymphoma, with a poor prognosis, derived from mature B cells that often do not enter the follicular germinal center and that often present aberrantly high cyclin D1-driven CDK4 activity." (PMID 36291856, 2022). "Focal cyclin-D1 expression is known to occur in up to 30% of cases of CLL/SLL, and this finding should be recognized in order to avoid misdiagnosing such cases as mantle cell lymphoma, which may drastically alter the course of patient management." (PMID 30687741, 2018). "Mantle cell lymphoma (MCL) is an aggressive non-Hodgkin B-cell lymphoma typically expressing CD19, CD20, CD5, FMC-7, CyclinD1, and SOX-11 and harboring the IgH/CCND1 translocation." (PMID 30627460, 2018). "Review of both cases showed findings consistent with chronic lymphocytic leukemia/small lymphocytic lymphoma (CLL/SLL), and both cases had scattered cyclin-D1 positive cells predominantly within proliferation centers, rather than the diffuse staining typically seen in cases of mantle cell lymphoma." (PMID 30687741, 2018). "The negative cyclin D1 argued against a mantle cell lymphoma." (PMID 27213065, 2016). "Meanwhile, lenalidomide was found to have inhibiting function of tumor growth through PI3K/Akt pathway, cereblon/p21, cyclin D1/p27 and Bcl-2 in chronic lymphocytic leukemia (CLL) and mantle cell lymphoma (MCL) in pre-clinical experiments." (PMID 27009084, 2016). "Furthermore, there can be CD5-negative mantle cell lymphomas and cyclin D1-negative (BCL1-negative) mantle cell lymphomas too." (PMID 23691402, 2013).
mantle cell lymphoma (continued). "Loss of miR-16-1 binding sites due to translocation of CCND1 (cyclin D1) and truncation of its 3′UTR contributes to its overexpression in mantle cell lymphomas (MCL)." (PMID 21698185, 2011). "Comparison of key immunophenotypic markers (CD5, CD10, CD23, CD25, CD103, cyclin D1) to differentiate chronic lymphocytic leukemia (CLL), mantle cell lymphoma (MCL), follicular lymphoma (FL), hairy cell leukemia (HCL), and splenic diffuse red pulp lymphoma (SDRPL)." (PMID 40585661, 2025). "CD5+ DLBCL can be differentiated from pleomorphic and blastoid mantle cell lymphoma (MCL) by the absence of cyclin D1 and SOX11." (PMID 39684922, 2024). "Mantle cell lymphoma (MCL) is an uncommon non-Hodgkin lymphoma (NHL) subtype, marked by presence of the t (11:14) translocation in more than 90% of the cases, which leads to overexpression of cyclin D1." (PMID 33648463, 2021). "Moreover, CD5, CD23, CD10, CD21, BCL-6, and Cyclin D1 were all negative, which could exclude the diagnosis of small lymphocyte lymphoma, follicular lymphoma, and mantle cell lymphoma." (PMID 33585230, 2020). "In addition, mantle cell lymphoma expresses cyclin D1 and BCL2 but negative for CD10." (PMID 25002984, 2014). "Negative staining for cyclin D1/SOX11 and CD10/BCL6 is useful for distinguishing MALT lymphoma from mantle cell lymphoma and follicular lymphoma, respectively." (PMID 40831827, 2025). "It is distinguished from follicular lymphoma by negativity for CD10 and Bcl-6, from mantle cell lymphoma by negativity for CD5 and Cyclin D1, and from nodular sclerosing Hodgkin lymphoma by lack of CD30-positive lacunar cells (Reed–Sternberg cells)." (PMID 28353588, 2017). "The possibility of transformation from mantle cell lymphoma is low due to positive CD23 and negative cyclin D1 expression." (PMID 27777803, 2016). "The SRY (sex determining region Y)-box 11 (SOX11) transcription factor was recently discovered as a new marker in mantle cell lymphoma (MCL), expressed in both cyclin D1 positive and negative cases." (PMID 21124928, 2010). "The negative CD5, CD23, and CD200 may exclude the diagnosis of chronic lymphocytic leukemia/small cell lymphoma, and the negative CD5, Cyclin D1, FMC7, and SOX-11 can exclude the possibility of mantle cell lymphoma." (PMID 38335376, 2024). "By IHC, mantle cell lymphoma is positive for CD5 and cyclin D1 and is negative for CD10 and CD23." (PMID 37958219, 2023).